CCL7 (C-C motif chemokine ligand 7)
Diseases named in the same sentence as CCL7 in open-access papers (continued):
Sharing a sentence is not in itself a finding about the gene and the disease.
cancer (continued). "Even though there is no previous evidence in the literature for CCL7 abolishing immunoglobulin expression specifically during cancer progression, it was reported that MSC–derived CCL2 suppresses plasma cell immunoglobulin production via STAT3 inactivation and PAX5 induction." (PMID 30764543, 2019). "In addition, the higher ratios of IFNα2 to Th2 cytokines, including IFNα2/IL4, IFNα2/IL10, IFNα2/CCL2, IFNα2/CCL7, IFNα2/CCL11, and IFNα2/TNFα, were associated with increased odds of ER negative vs. ER positive cancer." (PMID 24473087, 2014). "In addition, via binding to CCR3, CCL7 overexpression activates the ERK/JNK signaling pathway that converges on the downstream pathways of the MAPK cascade, thereby participating in the epithelial-mesenchymal transition (EMT) process that is sufficient to strengthen cancer metastasis capabilities." (PMID 29915688, 2018).
inflammation (9 papers, 2012 to 2024). Aberrant reaction of the microcirculation characterized by movement of fluid and leukocytes from the blood into extravascular tissues. "GM-CSF promotes the influx of myeloid cells, CCL2 is known to recruit monocytes, CCL3 has a role in lung inflammation and lymphocyte recruitment, and CCL7 can be linked to acute neutrophilic lung inflammation." (PMID 37600776, 2023). "The chemokines CCL2 and CCL7 are known as chemotactic agents for monocytes and they have been found to play a key role in mediating lung inflammation." (PMID 33076408, 2020). "CCL7 has also been shown to promote neutrophil recruitment in lung inflammation." (PMID 26046767, 2015). "Bindarit is an anti-inflammatory agent that inhibits MCP-1/CCL2, MCP-3/CCL7 and MCP-2/CCL8 synthesis, acting through the down-regulation of NF-kB pathway, that shows potent anti-inflammatory activity in animal models of both acute and chronic inflammation." (PMID 23077623, 2012).
cardiovascular disease (5 papers, 2018 to 2023). "Among them, CCR2 and its ligands, CCL2 and CCL7 play an important role, so the main objective of this work was to determine whether genetic variants affecting their activity were associated with cardiovascular disease." (PMID 35711383, 2022). "This review focuses on the emerging evidence on the roles of CCL7-related mechanisms in both experimental and clinical cardiovascular disease, DM, and kidney disease." (PMID 36109744, 2022). "This discussion indicates that the role of CCL7 is still undefined in cardiovascular disease." (PMID 36109744, 2022). "Elevated CCL7 expression is observed in cardiovascular disease, DM, and kidney disease." (PMID 36109744, 2022).
bacterial infection (4 papers, 2010 to 2022). "CCL2 and CCL7 are both implicated in monocyte recruitment during bacterial infection with Listeria monocytogenes." (PMID 29953538, 2018).
adenocarcinoma (3 papers, 2020 to 2021). A common cancer characterized by the presence of malignant glandular cells. "In adenocarcinomas, the expression ratios (normal-to-pathological) of ACKR2 were positively correlated with all those chemokines while in polyps, with CCL3 and less markedly with CCL4 and CCL7." (PMID 33374792, 2020). "In the GC sample cohort from the TCGA (Stomach adenocarcinoma (TCGA, Firehose Legacy, n = 478)), the levels of several markers for macrophages (FN1, MRS1, CD68, and CCL7), blood vessels (CDH5) and lymphatic vessels (VEGFC) exhibited positive correlations with TGM2 expression." (PMID 32467608, 2020).
immune diseases (2 papers, 2018 to 2021). "Abnormal CCL7 expression is associated with certain immune diseases." (PMID 29915688, 2018).
infectious disease (2 papers, 2012 to 2024). A disorder directly resulting from the presence and activity of a microbial, viral, or parasitic agent in humans. "Notably, the induction of the cognate chemokine ligands such as CCL2, CCL7, and CCL8 are regulated by IFNs-I in certain infectious diseases." (PMID 22911155, 2012).
kidney disease (2 papers, 2022 to 2023). "Due to the multiple redundancy system among chemokines and their receptors, further experimental and clinical studies should be interesting to focus on direct anti-CCL7 mechanisms as a promising therapeutic approach to attenuating the development of cardiovascular disease DM, and kidney disease." (PMID 36109744, 2022). "Therefore, CCL7 may contribute to the development of kidney fibrosis in different types of kidney diseases." (PMID 36109744, 2022).
neurodevelopmental disorder (1 paper, 2021). A behavioral and cognitive disorder with onset during the developmental period that involves impaired or aberrant development of intellectual, motor, or social functions. "Specifically, cytokine and chemokine profiles alteration, which is derived from CCL2, CCL7, and CCL11 imbalance in our patients, may provoke this neurodevelopmental disorder." (PMID 34828266, 2021).
CCL7 also shares sentences with these, for which no sentence is quoted: influenza (9 papers); cyst (5); endometriosis (4); acute myocardial infarction (3); Cirrhosis (3); Coronary Heart Disease (3); dengue (3); disc degeneration (3); lung (3); lupus nephritis (3); lymphopenia (3); synovitis (3); type 2 diabetes (3); atrial fibrillation (2); bronchitis (2); chronic periodontitis (2); cognitive decline (2); cognitive deficits (2); dental caries (2); diabetic nephropathy (2); endophthalmitis (2); eosinophilia (2); Erythema (2); hyperferritinemia (2); Listeria monocytogenes infection (2); lung disease (2); lymphoma (2); metastatic melanoma (2); multiple myeloma (2); schistosomiasis (2).
A further 109 diseases each share a sentence with CCL7 in 1 paper.